INS (insulin)
Diseases named in the same sentence as INS in open-access papers (continued):
Sharing a sentence is not in itself a finding about the gene and the disease.
Insulin resistance (continued). "In the very early stages of insulin resistance, the pancreas may compensate this metabolic disturbance by excreting higher quantities of insulin." (PMID 20573222, 2010). "Whether a rise in plasma insulin level despite insulin resistance normalizes the baroreflex sensitivity in TDG+C rats has to be further clarified." (PMID 20804606, 2010). "A small pilot study of 9 patients with dyslipidemia and insulin resistance, tested through hyperinsulinemic euglycemic clamp (insulin dose, 200 mU/m minute), showed in all a relevant increase in insulin sensitivity (+28%; P = .008) 12 months after the switch from a PI to boosted atazanavir." (PMID 21490912, 2010). "It is suggested that endothelial dysfunction and impaired capillary recruitment can cause insulin resistance because the microvascular endothelium can not react properly to insulin and glucose disposal is decreased." (PMID 20634940, 2010). "Because a recent article had demonstrated how visceral fat redistribution, liver fat accumulation, low-grade inflammation, and aggravated insulin resistance are all adverse effects caused by HCTZ therapy, we plotted a glycemic index and an insulin index for our patient, which gave normal results." (PMID 20964809, 2010). "Several works demonstrated that ghrelin concentrations are negatively associated with fasting insulin levels, the prevalence of type 2 diabetes and insulin resistance in humans, regardless of race." (PMID 20700401, 2010). "Oral administration of 100 mg/kg of GA to high-fat diet-induced obese rats for 28 days led to significant reduction in blood glucose concentration and improvement in insulin sensitivity as indicated by the homeostasis model assessment of insulin resistance (HOMA-IR) (p < 0.05)." (PMID 20670429, 2010). "The concordance of results showing that neither 6-Ac-Cas nor NButGT cause insulin resistance in 3T3-L1 adipocytes strongly points to the insulin-desensitizing effects of PUGNAc arising from off-target effects." (PMID 20851343, 2010). "We hypothesise that the moderate carbohydrate, increased protein diet will be more effective than the high carbohydrate diet in improving insulin sensitivity and metabolic profile in adolescents with clinical features of insulin resistance and/or prediabetes." (PMID 20868506, 2010). "In accordance with insulin's negative effects, hyperinsulinemia associated with hepatic or skeletal-muscle insulin resistance and/or obesity correlates inversely with fasting ghrelin concentrations." (PMID 20798846, 2010). "The chronic administration of NBS during 4 weeks might produce long-term effects which could reduce fasting insulin levels and insulin resistance on these subjects." (PMID 20623003, 2010). "A significant difference (p < 0.05) between the 2 groups was found in the treatment-induced changes in fasting insulin, the insulin resistance index HOMA, HDL cholesterol, triglycerides, diastolic blood pressure (all in favor of pioglitazone) and in body weight (increase with pioglitazone)." (PMID 20863381, 2010). "However, given reports of metabolically-benign obesity and the belief that insulin resistance drives the increased risk of cardiovascular events in obese individuals, we assessed the utility of LFP >4% in identifying insulin-resistant patients." (PMID 20553596, 2010). "OPN KO mice fed NC had greater hepatic insulin sensitivity than WT mice and were protected from 2 week HFD-induced insulin resistance in skeletal muscle, liver, and adipose, as measured by hyperinsulinemic-euglycemic clamp and by insulin-stimulated Akt phosphorylation." (PMID 21103061, 2010). "These are interesting, as prior studies have demonstrated that the related lipid molecules diacylglycerols (DAG), long-chain fatty acyl CoAs, and ceramides correlate positively with triglyceride content and inversely with insulin sensitivity and have been shown to induce insulin resistance." (PMID 20369014, 2010).
Insulin resistance (continued). "Ceramide may also activate protein phosphatase 2A, which inactivates PKB/Akt and attenuates insulin response, contributing to insulin resistance." (PMID 20706689, 2010). "Similarly, the roles of toll-like receptors, CD14, and rho kinases in regulating insulin signaling and establishment of insulin resistance in response to chronic low-grade inflammation are well documented." (PMID 20064776, 2010). "Furthermore, TNF α is over expressed in adipose tissue and induces insulin resistance through acute and chronic effects on insulin-sensitive tissues." (PMID 20396393, 2010). "Insulin Resistance (IR), an impaired metabolic response to circulating insulin resulting in a decreased ability of the body to respond to the hormone by suppressing Hepatic Glucose Output and enhancing tissue glucose uptake, plays a central role in the development of Type 2 Diabetes Mellitus." (PMID 20298586, 2010). "The mechanism whereby IMCL induces insulin resistance is unclear, but may be associated with diacylglycerol (DAG) and ceramide accumulation, lipid metabolites known to inhibit insulin signaling, in myotubes." (PMID 21143876, 2010). "Since one of the major effects of chronic ethanol exposure is hepatic insulin resistance leading to impairments in energy metabolism, repair, and regeneration, we assessed the influence of genetic strain on insulin and IGF receptor binding in relation to chronic ethanol exposure." (PMID 20814553, 2010). "These indices of insulin resistance necessitate serum insulin and glucose measurements, may require complex calculations, and have not yet made major inroads into general medical practice." (PMID 20507559, 2010). "The decreased amount of MAP kinase expression could lead to a decreased serine/threonine phosphorylation of for example the IRS proteins, ultimately increasing insulin signaling activity as part of a compensatory mechanism directed against insulin resistance." (PMID 19668377, 2009). "However, chronic elevations of insulin consequent to insulin resistance typically go along with high VLDL secretion and correspondingly high circulating TG." (PMID 19401758, 2009). "For the total patient cohort, serum resistin was correlated to insulin resistance as calculated by the HOMA-IR (homeostasis model assessment for insulin resistance) index and inversely correlated with glucose and insulin at admittance prior to intensive care interventions." (PMID 19545363, 2009). "Furthermore, these cells exhibit mTORC1-driven insulin resistance, as detected by a decrease in the insulin-stimulated phosphorylation of Akt, which is rescued by pre-treatment with rapamycin." (PMID 19593385, 2009). "Elucidation of the molecular mechanisms beneath the insulin-independent glucose uptake in KRAP−/− mice may lead to the development of medicines for patients suffering from insulin resistance." (PMID 19156225, 2009). "Importantly, these drug-like molecules are efficacious in improving glucose and insulin homeostasis in multiple animal models of insulin resistance and T2DM." (PMID 19284563, 2009). "In addition, there is only hepatic insulin resistance whereas insulin stimulated glucose uptake remained similar in both groups." (PMID 19680547, 2009). "We sought to develop a simple screening strategy to identify lean insulin-sensitive and obese-insulin resistant baboons for inclusion in genetic, physiologic and pharmacologic studies of obesity and insulin resistance using morphometric and biochemical markers of adiposity and glucose metabolism." (PMID 19389241, 2009). "The mechanism of insulin resistance in patients with Klinefelter syndrome is unknown, but has been suggested to be primarily mediated by a decrease in insulin sensitivity due to increased truncal obesity and decreased muscle mass secondary to hypogonadism." (PMID 19830242, 2009).
Insulin resistance (continued). "Her past medical history was remarkable for intermittent use of insulin and allergic reactions to several drugs, and measure of plasma anti-insulin antibodies level corroborated the clinical suspicion of immune mediated insulin resistance (8074 nU/ml - RIA - Ref value: <60)." (PMID 19941665, 2009). "Glucocorticosteroids may have a stimulating effect on leptin via the induction of insulin resistance, as glucose and insulin are also able to induce leptin expression." (PMID 19344528, 2009). "• Further studies are needed to discern whether treatment of CIH with insulin improves outcomes in critically ill children with peripheral insulin resistance and/or beta-cell dysfunction." (PMID 19245691, 2009). "Increased expression of insulin signaling molecules could possibly work in concert with increased levels of insulin protecting these individuals from insulin resistance and metabolic dysregulation." (PMID 19668377, 2009). "There are other factors causing insulin resistance, known to be involved in elevated IRS-1 serine phosphorylation including tumor necrosis factor α (TNF-α), free fatty acids, cellular stress, amino acids, and insulin." (PMID 19169352, 2009). "Finally, this study evaluates insulin signal proteins to investigate the mechanisms by which EA improves the insulin resistance of SBRs." (PMID 19646276, 2009). "Genetically and environmentally determined mitochondrial function may define a 'tipping point' where protective insulin resistance tips over to inflammatory insulin resistance." (PMID 19371409, 2009). "Thus, this study aimed to examine the relationship between paternal insulin sensitivity and parameters of early growth in the offspring as a means of exploring the genetic mechanism linking insulin resistance with low birth weight." (PMID 20062558, 2009). "Recently, using the hyperinsulinemic euglycemic clamp technique, we characterized the baboon as a model of insulin resistance and identified key biochemical and molecular defects in the insulin signaling cascade in some target tissues (skeletal muscle and adipose tissue)." (PMID 19389241, 2009). "However, a large dose of prednisolone increased insulin resistance, and this study successfully establishes a method of evaluating the effect of EA in improving insulin sensitivity in an insulin resistant state." (PMID 19646276, 2009). "Systemic insulin resistance has been associated with elevation of serum RBP4, whereas genetic and pharmacological interventions aimed at decreasing serum RBP4 levels enhance insulin action and improve insulin sensitivity." (PMID 19460132, 2009). "If this hypothesis is correct, then variable imprinted Ca patterns and concomitant insulin pulsatility in healthy mice may reflect attempts by the islet to compensate for varying levels of endogenous insulin resistance." (PMID 20037650, 2009). "It should also be stressed that, aside from their impact on fat inflammation, CB2 receptors expressed by other insulin sensitive tissues, including skeletal muscle and liver may also contribute to insulin resistance." (PMID 19513120, 2009). "Finally, insulin resistance is maintained in skeletal muscle cell cultures started from biopsies taken from people with type 2 diabetes and insulin resistant individuals signifying that it is not only the surrounding milieu that causes the molecular defects." (PMID 19668377, 2009). "Mice with genetic deletion of PPARγ in skeletal muscle showed significantly increased whole-body insulin resistance, demonstrated either by insulin/glucose tolerance tests or by hyperinsulinemic euglycemic clamp studies, and developed dyslipidaemia, enlarged fat pads, and obesity on high-fat diet." (PMID 20182551, 2009).
Insulin resistance (continued). "PPARγ2Pro12Ala has also been found to increase insulin sensitivity in middle-aged and elderly Finns and this finding is confirmed by subsequent studies in other populations, assessed by plasma levels of insulin and homeostasis model assessment of insulin resistance (HOMA-IR)." (PMID 19390629, 2009). "Meta-analysis of such studies confirmed a significantly lower levels of fasting insulin in subjects with the homozygous Ala12Ala genotype compared to the Pro12Pro genotype and significantly greater fasting glucose levels and insulin resistance in obese subjects in the Pro12Pro group." (PMID 19390629, 2009). "By analysing the data in this way, we could not detect any reliable association of the candidate SNPs with the prediabetes traits obesity, insulin resistance, or impaired insulin secretion." (PMID 18714373, 2008). "In addition, high doses of IKKβ inhibitors such as aspirin and salicylatereverse insulin resistance by sensitizing insulin signaling in obese rodents." (PMID 18566691, 2008). "Using our thoroughly phenotyped cohort of subjects at an increased risk for type 2 diabetes, we assessed the association of common genetic variation within the MTNR1B locus with obesity and prediabetes traits, namely impaired insulin secretion and insulin resistance." (PMID 19088850, 2008). "Overproductionof IAPP in insulin resistance may occur due to common transcription regulatory elements inthe promoter regions of the IAPP and insulin genes, and this might underly theenhanced amyloid formation in DM2." (PMID 18497871, 2008). "Obesity is strongly linked to insulin resistance and several studies have highlighted the correlation between adipocyte size rather than adipose tissue mass and insulin malfunction." (PMID 18320034, 2008). "In addition, other cell culture models of insulin resistance, such as osmotic stress or chronic exposure to insulin or IGF1 (IGF-1), have been shown to promote degradation of IRS2 in NIH3T3 cells." (PMID 19007436, 2008). "Because insulin resistance phenotype results from the cumulative effects of several contributing genetic alterations, I chose to focus on the genetic differences in candidate genes along the insulin signaling and inflammatory pathways." (PMID 18570670, 2008). "Numerous mechanisms contribute to insulin sensitivity regulation in several tissues (skeletal muscles, fat, liver), thus making difficult pathophysiological investigations into the manifestation of insulin resistance in humans." (PMID 18301746, 2008). "In both groups, serum insulin and glucose levels increased compared to the measurement made at the outset of the study, showing the effect of the dietary intervention in promoting insulin resistance." (PMID 18773087, 2008). "Basal glycerol release did not correlate with insulin sensitivity, and consistent with underlying insulin resistance in this obese cohort, hyperinsulinemia failed to suppress glycerol release (180±50 (basal) vs. 153±10μmol/L (steady state), p=ns)." (PMID 18340018, 2008). "Using our thoroughly phenotyped cohort of subjects at an increased risk for type 2 diabetes, we assessed the association of the nine latest genetic variants with the predominant prediabetes traits, i.e., obesity, impaired insulin secretion, and insulin resistance." (PMID 18714373, 2008). "One of the mechanisms by which high salt might precipitate insulin resistance is through its ability to enhance an oxidative stress-induced inflammatory response that disrupts the insulin signaling pathway." (PMID 18570670, 2008). "Thus, a systemic defect in the phosphatidylinositol 3–kinase pathway, which likely defines insulin resistance, leads to a combined defect in insulin-mediated glucose transport and in insulin stimulated endothelial vasodilation." (PMID 18949082, 2008).
Insulin resistance (continued). "These mutations have been associated with glucose transporters deficiency, lower serum insulin levels, glucose malabsorption and NIDDM making them attractive molecular targets for insulin resistance and glucose abnormalities (For review, the Human Gene Mutation Database)." (PMID 18570670, 2008). "Microvascular dysfunction is a cardinal feature of the metabolic syndrome that affects pressure and flow patterns, increasing peripheral vascular resistance and decreasing sensibility for insulin-mediated glucose disposal, contributing to hypertension and insulin resistance, respectively." (PMID 18949082, 2008). "Thus, if one wants to use fasting insulin to assess the state of insulin resistance, it is necessary to develop different cut-points for every assay." (PMID 18307789, 2008). "Another possible mechanism leadingto insulin resistance might be an upregulation of protein-tyrosine phosphatases(PTPases), capable of functioning as negative regulators of the insulin-triggeredpathway." (PMID 18604303, 2008). "Unlike tyrosyl phosphorylation, serine phosphorylation of IRS proteins attenuated insulin signaling and might potentially explain an additional mechanism of insulin resistance in rodents." (PMID 18570670, 2008). "GDM was hypothesized to result from pregnancy induced insulin resistance and impaired insulin secretion to compensate for it." (PMID 19015731, 2008). "The anti-natriuretic effect of insulin may be increased in individuals with insulin resistance and this effect may play an important role for development of hypertension." (PMID 18949082, 2008). "Because insulin resistance is characterized by a marked reduction in insulin-stimulated PI3K-mediated activation of Akt, we asked whether MES could increase Akt phosphorylation and ameliorate insulin resistance." (PMID 19114996, 2008). "Our findings highlight the impact of genetic differences on the regulation of insulin secretion and action, and the complex pathophysiological patterns of adaptations to HFD feeding, which underlie nutrigenomic predispositions to insulin resistance and obesity." (PMID 18301746, 2008). "Moreover, MUFA-rich diet prevents central fat redistribution and the postprandial decrease in peripheral adiponectin gene expression and insulin resistance induced by a carbohydrate-rich diet in insulin-resistant subjects." (PMID 18950537, 2008). "Therefore fasting and acute insulin injection in Dahl S rats (a model of insulin resistance) were additive in enhancing the insulin signaling pathway." (PMID 18570670, 2008). "Therefore, although other studies are needed, allthese observations suggest that a reduction of insulin-mediated intracellularsignaling is crucial for the establishment of insulin resistance." (PMID 18604303, 2008). "Although the pathogenesis of insulin resistance is largely unknown, studies have proven that it is due to a defect in insulin signaling." (PMID 19114996, 2008). "Insulin resistance, obesity and type II diabetes mellitus may result from defects in the insulin signaling system and are often accompanied by abnormalities in insulin degradation." (PMID 18477391, 2008). "Exercise decreases insulin resistance and thus circulating insulin levels." (PMID 18506190, 2008). "Fasting plasma insulin concentration correlates with insulin resistance." (PMID 18682834, 2008). "In future, cancer prevention and treatment strategies could revolve around insulin and insulin resistance." (PMID 17953765, 2007). "On the one hand insulin resistance is associated with a series of fatal disorders and centenarians are known to have high insulin sensitivity, but on the other, the Klotho gene whose overexpression is known to increase lifespan has been shown to act by increasing insulin resistance." (PMID 17437648, 2007). "Insulin resistance is a condition in which tissues exhibit reduced response to insulin." (PMID 17437648, 2007).